PCSK9 (proprotein convertase subtilisin/kexin type 9)
Diseases named in the same sentence as PCSK9 in open-access papers (continued):
Sharing a sentence is not in itself a finding about the gene and the disease.
acute coronary syndrome (106 papers, 2014 to 2026). Signs and symptoms related to acute ischemia of the myocardium secondary to coronary artery disease. "The PCSK9-REACT study demonstrated that elevated PCSK9 levels in acute coronary syndrome patients on dual antiplatelet therapy are associated with increased platelet reactivity, reduced antiplatelet efficacy and higher risk of major cardiovascular events." (PMID 41590245, 2026). "Nevertheless, the use of cholesterol-lowering drugs, such as statins or fibrates, in melanoma is controversial, specifically in terms of its potential to increase PCSK9, which is associated with platelet reactivity, leading to acute coronary syndrome." (PMID 37046831, 2023). "Two major cardiovascular outcome trials showed that the use of the PCSK9 inhibitors (alirocumab and evolocumab) in patients with recent acute coronary syndrome (ACS) is associated with a lower risk of further cardiovascular (CV) events." (PMID 36895542, 2023). "As PCSK9 antagonism was more efficient in patients with acute coronary syndrome when they displayed metabolic risk factors, we investigated the effect of the genetic deletion of PCSK9 on I/R injury in vivo in mice fed normal diets or high-fat diets." (PMID 35742954, 2022). "On the other hand, in patients with acute coronary syndrome, PCSK9 levels were associated with hsCRP." (PMID 35806908, 2022). "Accordingly, PCSK9 was associated with increased platelet aggregation in patients with acute coronary syndrome and treatment with anti-PCSK9 mAb was found to modulate platelet reactivity." (PMID 32252393, 2020). "A positive association with PCSK9 and cardiovascular events was found in the general population, in FH subjects, and in patients with acute coronary syndrome or stable CAD." (PMID 33023603, 2020). "Alirocumab is a fully human monoclonal antibody to PCSK9 that reduces the risk of recurrent ischemic cardiovascular events in patients with acute coronary syndrome when administered on top of atorvastatin." (PMID 31843957, 2020). "Recent data suggest that circulating levels of PCSK9 increase within hours of the onset of acute coronary syndrome (SCA) and are associated with increased platelet anti-aggregation, the vulnerability of coronary plaque, elevated inflammatory markers, and higher long-term cardiovascular events." (PMID 38610647, 2024). "Long-term mortality risk following acute coronary syndrome may be reduced with PCSK9-i when combined with intensive statin therapy." (PMID 37898751, 2023). "PCSK9 is positively associated with platelet reactivity, which may partly account for the beneficial effect of PCSK9 inhibition in reducing the risk of major adverse cardiovascular events after acute coronary syndrome (ACS)." (PMID 36324757, 2022). "Moreover, in patients undergoing coronary angiography for acute coronary syndrome or stable angina, PCSK9 was found to linearly associate with the fraction and amount of necrotic core tissue in coronary atherosclerosis, independently of serum LDL cholesterol levels and statin use." (PMID 34336112, 2021). "Clinically, PCSK9 levels increase rapidly after acute cardiovascular events, such as acute coronary syndromes, due to its role in regulating LDL receptor degradation in hepatocytes." (PMID 41590245, 2026). "Multiple recent studies and systematic reviews support the safety and efficacy of early, in-hospital initiation of PCSK9 inhibitors in patients with acute coronary syndrome (ACS)." (PMID 41010649, 2025). "A study has shown that intensive TG reduction along with TC and LDL-C lowering with PCSK9 inhibitor gradually provide additional deferred improvement in coronary flow in IRA 6 months after coronary angioplasty for acute coronary syndrome." (PMID 40863381, 2025). "The ODYSSEY OUTCOMES trial evaluated alirocumab, a PCSK9 inhibitor, in 18,924 patients with recent acute coronary syndrome (ACS) who were already on high-intensity or maximum tolerated statin therapy." (PMID 41010649, 2025).
acute coronary syndrome (continued). "There are several recent or ongoing studies examining the early use of PCSK9 inhibitors in acute coronary syndrome patients undergoing percutaneous coronary intervention with anticipated extra-LDL reduction and other pleiotropic effects." (PMID 38817546, 2024). "This systematic review and meta-analysis study aims to assess the effectiveness of PCSK9 inhibitors as plaque stabilizers for secondary prevention following acute coronary syndrome (ACS)." (PMID 39365518, 2024). "Among them, the top three clusters were “PCSK9,” “Acute Coronary Syndrome,” and “Familial Hypercholesterolaemia”." (PMID 39650150, 2024). "The study seeks to assess the safety and effectiveness of PCSK9 inhibitors in individuals who have been treated with statins after experiencing acute coronary syndrome (ACS), as well as investigate the impact on the characteristics of coronary plaque." (PMID 39365518, 2024). "The findings also recommend the early application of PCSK9 inhibitors in patients with acute coronary syndrome." (PMID 39055658, 2024). "The combination of statin therapy and PCSK9 inhibitors (evolocumab and alirocumab) promotes plaque stability in patients following an acute coronary syndrome." (PMID 39150672, 2024). "Current active keywords include “low-density lipoprotein cholesterol,” “acute coronary syndrome,” “safety,” and “PCSK9 inhibitor,” indicating emerging research avenues." (PMID 38828451, 2024). "Our analysis comprised trials and observational studies that compared the plaque phenotype, lipid profile, and safety outcomes between PCSK9 inhibitors and a control group in patients with acute coronary syndrome who were already being treated with statins." (PMID 39365518, 2024). "This meta-analysis comprehensively evaluated the safety and effectiveness of PCSK9 inhibitors in patients who were already receiving statin treatment, with a specific focus on the use of plaque phenotyping data in patients with acute coronary syndrome (ACS)." (PMID 39365518, 2024). "The effect of proprotein convertase subtilisin kexin type (PCSK9) inhibitors on blood lipids and major adverse cardiovascular events (MACEs) is still controversial for acute coronary syndrome (ACS) patients." (PMID 39259104, 2024). "PCSK9 levels were also accurate when used to predict acute coronary syndrome (ACS) at 24-month follow-up in patients with severe carotid artery atherosclerosis undergoing carotid endarterectomy." (PMID 37620933, 2023). "PCSK9 expression is positively correlated with cardiovascular events in patients with acute coronary syndrome." (PMID 38115042, 2023). "On the other hand, it was established that hs-CRP is positively correlated with PCSK9 concentrations in chronic coronary disease and acute coronary syndrome." (PMID 37765005, 2023). "As a type of PCSK9 inhibitor, evolocumab was administered on a large scale to treat acute coronary syndrome (ACS)." (PMID 36051574, 2022). "A strong correlation between PCSK9 levels and platelet reactivity was also revealed in patients with recent acute coronary syndromes who underwent coronary intervention and received P2Y12 inhibitors." (PMID 36324757, 2022). "In the ODYSSEY Outcomes randomized clinical trial, statin-treated patients with recent acute coronary syndrome received the PCSK9 inhibitor alirocumab." (PMID 35806908, 2022). "Proprotein convertase subtilisin/kexin type 9 inhibitors: Early effects on cardiovascular events in patients post-acute coronary syndrome?" (PMID 36568547, 2022). "In humans, PCSK9 inhibitors therapy added to statin therapy is capable of increasing fibrous cap thickening in acute coronary syndrome patients, reducing plaque vulnerability." (PMID 33834043, 2021).
acute coronary syndrome (continued). "Recently, a direct correlation of PCSK9 plasma levels and hyperreactivity of platelets in patients with acute coronary syndrome has been described." (PMID 34681838, 2021). "The Evolocumab for Early Reduction of LDL‐Cholesterol Levels in Patients With Acute Coronary Syndromes (EVOPACS) trial was the first to assess PCSK9 inhibitor antibody treatment during the acute phase of ACS." (PMID 33760276, 2021). "This analysis therefore suggests that PCSK9 inhibition has the potential to reduce mortality after acute coronary syndrome with longer treatment than in the main study, and especially in patients with elevated risk due to high LDL-C." (PMID 33304274, 2020). "ODYSSEY OUTCOME (Evaluation of Cardiovascular Outcomes After an Acute Coronary Syndrome During Treatment With Alirocumab) randomized trial demonstrated that PCSK9 inhibitor alirocumab reduced Lp(a) by a median 23.5% after 4 months." (PMID 33613445, 2020). "This study was the first to show safety of initiating PCSK9 inhibitor treatment during hospitalization for acute coronary syndrome." (PMID 33304274, 2020). "Alirocumab is another PCSK9 inhibitor which was tested in more than 18,000 patients presenting with acute coronary syndrome with baseline LDL-c of 87 mg/dL." (PMID 33060939, 2018). "Future studies should explore whether triple therapy (statin+bempedoic acid+PCSK9 inhibitor) could provide incremental benefits in acute coronary syndromes." (PMID 41481564, 2026). "The EVACS (Evolocumab in Acute Coronary Syndrome) trial investigated the safety, feasibility, and efficacy of initiating the PCSK9 inhibitor evolocumab during hospitalization for acute coronary syndrome (ACS), specifically targeting patients with non-ST-elevation myocardial infarction (NSTEMI)." (PMID 41010649, 2025). "Finally, plasma levels of SIRT1 and PCSK9 were assessed at baseline in patients with acute coronary syndromes." (PMID 40653676, 2025). "Furthermore, evidence suggests that early administration of PCSK9 inhibitors in acute coronary syndrome patients can lead to rapid lipid control and attenuation of systemic inflammation." (PMID 40727466, 2025). "Recent research has shifted its focus toward the feasibility of applying PCSK9 inhibition therapy to patients with acute coronary syndrome (ACS) as soon as possible, as both serum and ischemic myocardial PCSK9 levels surge rapidly during ACS, potentially contributing to acute inflammatory reactions." (PMID 39139638, 2024). "The feasibility, safety, and efficacy of PCSK9 antibody treatment during acute coronary syndrome in patients who have undergone CABG are presently unknown." (PMID 38337601, 2024). "Key studies comparing PCSK9 inhibitors to placebo in patients with acute coronary syndromes." (PMID 39274253, 2024). "In patients with acute coronary syndrome, PCSK9 concentrations did not appear to be a predictive risk factor for recurrent cardiovascular events within one year." (PMID 36768292, 2023). "The results of this study point to a possible advantage of PCSK9 inhibition in the early stages of acute coronary syndrome (ACS), particularly for patients with DM and high PCSK9 levels, by a dual mechanism on both lipid-lowering and inflammation/platelet pathways." (PMID 37765005, 2023). "However, we must consider that patients who were already treated with statins at the time of their first acute coronary syndrome had significantly higher concentrations of PCSK9 that further increased during the first year." (PMID 36768292, 2023). "Prior research had demonstrated that PCSK9 may behave as an acute phase reactant in acute coronary syndromes, and that its synthesis and secretion may be stimulated by hsCRP in vitro." (PMID 35864531, 2022). "However, the effects of evolocumab, an approved PCSK9 monoclonal antibody, on lipid reduction and inflammation regulation in Chinese patients with acute coronary syndrome (ACS) during their in-hospital stage after an index event are not well known." (PMID 36017088, 2022).
acute coronary syndrome (continued). "Also, the circulating concentration of Pcsk9 increased in the first few hours/days after acute coronary syndrome (ACS)." (PMID 34044829, 2021). "Low levels of PCSK–9 (or inhibition of PCSK–9) could therefore exert beneficial effects–Of note, all patients included in this analysis had an acute coronary syndrome as cause of cardiac arrest." (PMID 32796672, 2020). "PCSK9 inhibition with alirocumab has been shown to strongly lower LDL-C and non-HDL-C alone and on top of statin, and reduce the risk of recurrent ischemic cardiovascular events in patients with acute coronary syndrome." (PMID 31843957, 2020). "In the recent study about proprotein convertase subtilisin–kexin type 9 (PCSK9) inhibitor use for secondary prevention after acute coronary syndrome, the patients with lower LDL-C level had better outcomes about recurrent ischemic cardiovascular events during the longer follow-up period." (PMID 31905621, 2019). "In patients with acute coronary syndrome, high plasma levels of PCSK9 correlate with inflammation." (PMID 28439730, 2017). "PCSK9 MaB (Proprotein Convertase Subtilisin/Kexin Type 9Inhibitor) may reduce the occurrence of major adverse cardiovascular events(MACEs) in patients diagnosed with acute coronary syndrome (ACS)." (PMID 39076939, 2024). "Adding proprotein convertase subtilisin/kexin type 9 (PCSK9) inhibitors to moderate- or high-intensity statin therapy regimens leads to cardiovascular risk reduction in patients with stable atherosclerotic cardiovascular disease, or after recent acute coronary syndromes." (PMID 35890138, 2022). "Firstly, PCSK9 is able to induce the secretion of proinflammatory cytokines in macrophages and in other various tissues and elevated serum PCSK9 levels could be observed in pro-inflammatory conditions, such as sepsis, acute coronary syndrome (ACS)." (PMID 35252378, 2022). "Moreover, all of these studies took into account blood samples collected in acute cardiovascular conditions, such as acute coronary syndrome or a worsening of HF that could have affected the circulating levels of both NPs and PCSK9." (PMID 36009507, 2022). "PCSK9 inhibitors have been reported to have a rapid effect, a vast range of lipid reduction, a long duration of action, and an anti-inflammatory effect, providing a new dawn for further reducing MACEs of acute coronary syndrome (ACS) patients who underwent PCI." (PMID 36632288, 2022). "Evolocumab and alirocumab, as the first-generation PCSK9 inhibitors, are now widely used in patients with poor LDL-C control and acute coronary syndrome." (PMID 38828451, 2024). "Proprotein convertase subtilisin/kexin type 9 (PCSK9) regulates low-density lipoprotein (LDL) homeostasis and plays a key role in acute coronary syndrome (ACS)." (PMID 37058054, 2023). "Recently, in a large prospective multi-center study conducted in patients with acute coronary syndrome (ACS), patients with higher levels of circulating PCSK9 suffered a higher degree of acute phase inflammation assessed by hs-CRP levels." (PMID 35252378, 2022). "In PCSK9-REACT study, patients with acute coronary syndrome after percutaneous coronary intervention were treated with prasugrel or ticagrelor." (PMID 35806908, 2022). "The PCSK9-REACT study is an observational, prospective study where patients with recent acute coronary syndromes underwent coronary intervention and received P2Y12 inhibitors." (PMID 33834043, 2021). "In epidemiological studies, PCSK9 is positively correlated with inflammatory markers, such as CRP, white blood cell count and fibrinogenin patients with acute coronary syndromes." (PMID 34692791, 2021). "Proprotein convertase subtilisin/Kexin type 9 (PCSK9) inhibitors have been confirmed to lower Lp(a) and should be considered as an independent treatment after acute coronary syndrome." (PMID 34107870, 2021).
acute coronary syndrome (continued). "The procoagulant effect of PCSK9 may also play a pathogenetic role within the inflamed microenvironment of a disrupted atherosclerotic plaque by stimulating TF expression in resident macrophages favoring the formation of the occluding thrombus during acute coronary syndromes." (PMID 34884442, 2021). "Most current guidelines recommend starting PCSK9 inhibitors in patients with acute coronary syndrome (ACS) if LDL-C targets are not achieved after 4–6 weeks of maximally tolerated statin and ezetimibe therapy." (PMID 41010649, 2025). "The use of PCSK9 inhibitors has been assessed in the ODYSSEY Outcomes study, in which alirocumab was compared with placebo in 18,924 patients who had experienced recent acute coronary syndromes and were already receiving optimized statin therapy." (PMID 38610647, 2024). "Evaluation of Cardiovascular Outcomes After an Acute Coronary Syndrome During Treatment With Alirocumab (ODYSSEY OUTCOMES) trial results confirmed the effectiveness and safety of PCSK9 inhibitors compared with placebo using alirocumab, another PCSK9 inhibitor." (PMID 37109734, 2023). "The PCSK9-REACT study found that, in patients with a recent acute coronary syndrome (ACS) undergoing percutaneous coronary intervention and receiving P2Y12 inhibitor, there was a direct association between PCSK9 plasma level and high-on-treatment platelet reactivity." (PMID 36324757, 2022). "Early combination allows for the timely introduction of non-statin agents, such as ezetimibe and PCSK9 inhibitors, which have additive LDL-C lowering effects and improve plaque stabilization, thereby further reducing cardiovascular risk after an acute coronary syndrome (ACS)." (PMID 41010649, 2025). "For patients experiencing acute coronary syndrome (SCA) while on statin therapy, the first consideration should be the current drug and dosage: for those with a history of confirmed statin intolerance and SCA, prescribing ezetimibe 10 mg/day and a PCSK9 inhibitor is reasonable." (PMID 38610647, 2024). "Long-term CV outcome studies have shown that PCSK9 inhibitors reduce CV event rates similarly in individuals with and without T2DM and prior CV disease or recent acute coronary syndrome." (PMID 31706300, 2019). "Pro-protein convertase subtilisin/kexin type 9 (PCSK9) inhibitors have been studied in patients with acute coronary syndromes only after 2–3 months of treatment with statins and never in the acute phase (first month) of an acute coronary syndrome." (PMID 32375792, 2020).